SLC7A11 (solute carrier family 7 member 11)
Diseases named in the same sentence as SLC7A11 in open-access papers (continued):
Sharing a sentence is not in itself a finding about the gene and the disease.
hepatocellular carcinoma (continued). "Sorafenib has been repeatedly reported to induce ferroptosis through the inhibition of system Xc–, contradicting the claim from the latter study that sorafenib does not trigger ferroptosis through the inhibition of system Xc− due to low SLC7A11 expression in human hepatoma cell lines." (PMID 39507762, 2024). "Furthermore, Huang and colleagues illustrated that by blocking SLC7A11-induced ferroptosis in hepatocellular carcinoma, ABCC5 aids in the development of sorafenib resistance." (PMID 39315094, 2024). "Furthermore, in another research, Lyu and co-workers indicated that through the circ0097009/miR-1261/SLC7A11 axis, ferroptosis contributes to the progression of hepatocellular carcinoma." (PMID 39315094, 2024). "GPX4 and SLC7A11 are also important in hepatocellular carcinoma (HCC)." (PMID 38590315, 2024). "In summary, this is a first study to analysis disulfidptosis-related genes in hepatocellular carcinoma, and we identified that SLC7A11 and LRPPRC could be used as independent prognostic factors for HCC." (PMID 37399661, 2023). "Nevertheless, a latest study demonstrated that YAP/TAZ could induce the expression of SLC7A11 to inhibit ferroptosis and maintain the resistance of liver cell carcinoma to sorafini." (PMID 36046690, 2022). "Similarly, our previous study demonstrated that overexpressed SLC7A11 was validated as an oncogene in hepatocellular carcinoma." (PMID 35664306, 2022). "Sorafenib (SOR), a frontline hepatocellular carcinoma (HCC) therapeutic, induces ferroptosis through inhibition of solute carrier family 7 member 11 (SLC7A11)." (PMID 40744916, 2025). "METTL9 knockdown reduces the expression levels of SLC7A11, a key inhibitor of ferroptosis, thereby indirectly inducing ferroptosis in hepatocellular carcinoma (HCC)." (PMID 41194259, 2025). "The disulfidptosis-related gene SLC7A11 is proposed to potentially emerge as a new prognostic biomarker for hepatocellular carcinoma (HCC), presenting both opportunities and challenges for the development of personalized cancer immunotherapy strategies." (PMID 38685115, 2024). "Dihydroartemisinin (DHA) induces ferroptosis in hepatocellular carcinoma (HCC) by inhibiting ATF4, thus decreasing SLC7A11 expression and enhancing lipid peroxidation, also improving chemosensitivity to sorafenib, offering a novel therapeutic approach for HCC." (PMID 39315094, 2024). "In diethylnitrosamine-induced hepatocellular carcinoma mouse models, conditional deletion of activating transcription factor 4 (Atf4), an ER stress-related transcription factor, enhances ferroptotic liver damage by downregulating SLC7A11, thus promoting liver tumorigenesis." (PMID 38844964, 2024). "According to other reports, CDCA7 could enhance the activation of TGF-β and thereby promote ferroptosis of hepatocellular carcinoma cells by repressing the expression of SLC7A11 and enhancing lipid peroxidation, which is inconsistent with our inference that CDCA7 inhibits ferroptosis in gliomas." (PMID 37510310, 2023). "Paradoxically, in sorafenib-resistant hepatocellular carcinoma (HCC) models, FASN orchestrates nuclear accumulation of HIF1α to drive SLC7A11 transactivation, thereby conferring ferroptosis resistance." (PMID 40890129, 2025). "For instance, in hepatocellular carcinoma, USP8 inhibition induces ferroptosis by destabilizing OGT, thereby disrupting SLC7A11-mediated cystine uptake." (PMID 40813720, 2025). "The expression of SLC7A11 negatively correlates with ACC patients’ survival, as seen for several cancers, such as invasive breast cancers and hepatocellular carcinoma, among others." (PMID 40229247, 2025). "In hepatocellular carcinoma, the knockdown of AKR1C3 resulted in a decrease in YAP nuclear translocation, leading to the inhibition of cystine transporter SLC7A11." (PMID 38675549, 2024).
hepatocellular carcinoma (continued). "The results of Western Blot showed that curcumin decreased the expression of ferroptosis-related proteins SLC7A11, GSS, GPX4, and FTH1, as well as increased the expression levels of PTGS2 and ACSL4 in hepatocellular carcinoma tissues." (PMID 39311951, 2024). "It has been shown that CAPG regulates ferroptosis through SLC7A11-mediated GSH synthesis to promote cell proliferation, and the GSH level is decreased after CAPG knockdown in hepatocellular carcinoma." (PMID 39600941, 2024). "In hepatocellular carcinoma, AKR1C3 mediates the progression of ferroptosis by regulating the YAP/SLC7A11 signaling pathway, which is a novel treatment target for clinical therapy." (PMID 38577596, 2024). "DHA downregulated the SLC7A11 expression and reduced the GSH and GPX4 levels along with increasing the cellular lipid ROS level in lung cancer cells, hepatocellular carcinoma cells, and head and neck carcinoma cells." (PMID 39021832, 2024). "Meanwhile, hypoxia increases SLC7A11 by inhibiting methyltransferase-like 14 (METTL14) to suppress ferroptosis by decreasing ROS, which promotes hepatocellular carcinoma (HCC) progression." (PMID 37458878, 2023). "In hepatocellular carcinoma, PNO1 inhibition blocked SLC7A11 expression and the xCT activity followed cystine intake, which downregulated the accumulation of GSH and expression of GPX4 and induced ferroptosis." (PMID 37268653, 2023). "In order to evaluate the expression level of hub genes (HRAS, SLC7A11 and SLC2A1) in hepatocellular carcinoma, we conducted immunohistochemical (IHC) analysis." (PMID 37051544, 2023). "Similarly, survival probability in hepatocellular carcinoma was reliably predicted by a glioma prediction model (ACSL3, ACSL6, ACACA, G6PD, SLC1A5, SLC7A11 and VDAC2) and by a risk model with a strong overlap with the genes in the glioma models (G6PD, HMOX1, LOX, SLC7A11, STMN1/Stathmin 1)." (PMID 34926298, 2021). "A previous study revealed that 3 ferroptosis-related genes (SLC7A11, G6PD, CISD1) in hepatocellular carcinoma were upregulated in tumor tissue, and their high expression correlated with a poor prognosis." (PMID 33672990, 2021). "The results showed that PDSS1, SLC7A11 and CDCA8 were significantly upregulated in hepatoma cell lines (P < 0.05)." (PMID 32887635, 2020). "However, our study reveals that SLC7A11 infrequently presents with CNV and SNV, especially in hepatocellular carcinoma." (PMID 38397869, 2024). "At the same time, the activity of the SLC7A11/GPX4 axis, an anti-ferroptosis system in hepatocellular carcinoma cells, was also significantly inhibited by curcumin, which further exacerbated the degree of intracellular ferroptosis in hepatocellular carcinoma cells." (PMID 39311951, 2024). "that focused on hepatocellular carcinoma reported that YAP/TAZ, as a transcriptional coactivator, formed a complex with TEADs that indirectly bound the TEAD sequence in the SLC7A11 gene promoter, ultimately leading to upregulating the content of SLC7A11 and inhibiting the development of ferroptosis." (PMID 37266433, 2023). "For example, in hepatocellular carcinoma (HCC), YTHDF1 recognizes the m6A mark on SLC7A11 mRNA to enhance the inhibition of ferroptosis, and in hepatic stellate cells, YTHDF1 also recognizes m6A mark on the BECN1 mRNA, enhancing ferritinophagy to induce ferroptosis." (PMID 37229485, 2023). "It is reported that in the prognosis model of hepatocellular carcinoma, the genes (NFS1, CISD1, ACSL3, NQO1, SLC7A11, GPX4) that can protect hepatocytes with ferroptosis and the genes (ACACA, CARS, G6PD, SLC1A5) that induce ferroptosis are all up-regulated in HCC, and are related to poor prognosis." (PMID 36387286, 2022). "The genetic disruption or chemical inhibition of SLC3A2/ SLC7A11 HATC leads to autophagy and ferroptosis in the different types of tumor cells, including endometrial, colorectal, pancreatic cancer, and hepatocellular carcinoma (HCC) through inhibition of mTOR/p70S6K signaling." (PMID 33401748, 2021).
hepatocellular carcinoma (continued). "In human hepatocellular carcinoma (HCC) and hepatoblastoma cells, IGF2BP1 binds to the 3′UTR of SLC7A11 mRNA, enhancing its stability and preventing deadenylation." (PMID 40271153, 2025). "Gallic acid induces ferroptosis in hepatocellular carcinoma cells by inhibiting SLC7A11 and GPX4 expression and blocking the Wnt/β-catenin pathway, highlighting its potential as a therapeutic agent for HCC." (PMID 39315094, 2024). "METTL9 promotes hepatocellular carcinoma progression by inhibiting ferroptosis through upregulation of SLC7A11, with its knockdown significantly reducing tumor viability, migration, and invasion, suggesting METTL9 as a potential therapeutic target for HCC." (PMID 39315094, 2024). "It has been shown that IL-1β-induced solute carrier family 7 member 11 (SLC7A11) overexpression upregulates PD-L1 and colony-stimulating factor 1 (CSF1) through the α-ketoglutarate/HIF1α axis, promoting MDSCs recruitment and infiltration in the hepatocellular carcinoma tumor niche." (PMID 38609997, 2024). "It has been reported that IL-1 β increased the level of SLC7A11, then up-regulated the expression of PD-L1 and CSF1 by regulating α-KG/HIF1 α and promoted the infiltration of tumor-related macrophages and myeloid suppressor cells to increase the metastasis of hepatocellular carcinoma." (PMID 38137387, 2023). "In hepatocellular carcinoma (HCC), for instance, SOCS2 increases radiotherapy sensitivity by enhancing SLC7A11 ubiquitination and ferroptosis." (PMID 37795447, 2023). "Cancer cells exhibit the ability to prevent ferroptosis by expressing high levels of SLC7A11, which is regulated by NRF2, SOX2 in lung cancer stem-like cells, and YAP/TAZ pathway in hepatocellular carcinoma (HCC) leading to ferroptosis resistance." (PMID 36289191, 2022). "Ferroptosis-related proteins SLC7A11 and GPX4 participate in the regulation of the growth and proliferation of some types of carcinoma cells, such as lymphocytoma, ductal cell cancer of the pancreas, and hepatocellular carcinoma (HCC)." (PMID 37807410, 2023). "In addition, the measurements of ferroptosis characteristic indicators, such as the expression of SLC7A11 and GPX4, as well as the intracellular lipid peroxidation and Fe2+ concentration, indicate that high level of ferroptosis increases the radiosensitivity of hepatocellular carcinoma." (PMID 37714846, 2023). "For instance, in hepatocellular carcinoma (HCC), the increase in intracellular copper levels induced by ionizing radiation promotes the transcriptional activity of Hypoxia Inducible Factor 1 Subunit Alpha (HIF1A), thereby elevating the expression levels of ceruloplasmin and SLC7A11 within cells." (PMID 40200790, 2025).
glioma (135 papers, 2013 to 2026). A benign or malignant brain and spinal cord tumor that arises from glial cells (astrocytes, oligodendrocytes, ependymal cells). "Previous studies have indicated that gliomas exhibit high SLC7A11 expression, heightened metabolism, and glucose deficiency." (PMID 38504986, 2024). "It is interesting to note that SLC7A11 expression is upregulated in gliomas and associated with seizure occurrence in both human and animal tumors." (PMID 38641945, 2024). "Results reported in many studies indicate that the overexpression of SLC7A11 is associated with a glioma malignancy, thus making xCT one of the potential targets for the treatment of gliomas." (PMID 37175751, 2023). "In glioma cells, an increase in extracellular glutamate caused by overexpression of SLC7A11 impairs cytotoxic T-cell activation and promotes regulatory T (Treg)-cell proliferation, leading to intratumoral immunosuppression." (PMID 36552652, 2022). "In clinical studies, high expression of SLC7A11 in patients with pulmonary cancer, pancreatic cancer, liver carcinoma, thyroid carcinoma, melanoma, or glioma was associated with a poor prognosis." (PMID 33348858, 2020). "The enhanced glutamatergic drive is the result of glutamate (Glu) being assiduously released from gliomas via system Xc transporter (SXC) encoded by the SLC7A11 gene that is upregulated in about 54% of glioma patients." (PMID 30413686, 2018). "Moreover, high expression of SLC7A11 caused significant peritumoral glutamate excitotoxicity, resulting in glioma‐associated seizures and shorter overall survival." (PMID 39993959, 2025). "Furthermore, the upregulation of SLC7A11 (xCT), a subunit of the cystine–glutamate transporter system, in glioma cells has been associated with tumor invasion, outcomes in GBM patients, and the onset of seizures." (PMID 39201639, 2024). "Thus, it is important to elucidate the underlying mechanism by which SLC7A11 expression is regulated in glioma." (PMID 34927544, 2021). "Additionally, SLC7A11 overexpression is associated with the stem-cell like traits in glioma." (PMID 34927544, 2021). "SLC7A11 is overexpressed in several cancer types, including glioma and non-small cell lung cancer, and serves as an independent prognostic factor." (PMID 41249582, 2025). "Glioma cells primarily secrete Glu via the cystine/Glu antiporter solute carrier family 7 member 11 (SLC7A11 or xCT)." (PMID 40197808, 2025). "Several studies have shown that glioma cells upregulate the expression of SLC7A11, which regulates glutathione production and glioma growth." (PMID 40109666, 2025). "In fact, cystine/glutamate reverse transporters System Xc‐ and SLC7A11 have been intensively studied in gliomas." (PMID 39993959, 2025). "Nrf2 is a transcription factor that is sensitive to redox changes and capable of regulating the expression of the intracellular redox balance proteins GPX4 and SLC7A11 in glioma cells." (PMID 40109666, 2025). "Studies have shown that the expression of SLC7A11 in gliomas can contribute to tumorigenesis, progression and resistance to conventional chemotherapies." (PMID 39993959, 2025). "SLC7A11 expression in gliomas plays a significant role in tumorigenesis, tumor progression, and resistance to conventional chemotherapy." (PMID 40109666, 2025). "In glioma, hypoxia upregulates SLC7A11 via the PI3K/AKT/HIF-1α axis to enhance glioma resistance to salazosulfapyridine-induced ferroptosis." (PMID 38304870, 2024). "Spearman correlation analyses were employed to elucidate the interplay between SLC3A2, RPN1, NCKAP1, and SLC7A11 within the glioma landscape, revealing the strongest correlation between SLC3A2 and SLC7A11 (R = 0.242, P < 0.001)." (PMID 38977800, 2024). "On the molecular level, glutamate is released from the tumor cells in exchange for cystine via solute carrier family 7 member 11 (SLC7A11; xCT), an antiporter that was found to be upregulated in glioma." (PMID 38835368, 2024).
glioma (continued). "Univariate Cox regression analysis has discerned significant associations between glioma patient survival trajectories and the expression profiles of several disulfidptosis-related genes, specifically SLC3A2, RPN1, NCKAP1, and SLC7A11 (all, P < 0.05)." (PMID 38977800, 2024). "Our study shows that erastin treatment significantly downregulated the expression of GPX4 and SLC7A11, confirming the occurrence of ferroptosis in glioma cells." (PMID 39857625, 2024). "SLC7A11-mediated ferroptosis in glioma cells was involved in regulating the stemness maintenance of glioma cells." (PMID 38811540, 2024). "Ibuprofen, a clinically used NSAID, induces ferroptosis in glioma cells through inhibiting System Xc- activity by down-regulating SLC7A11 expression." (PMID 37580745, 2023). "Our data reveal that ectopic CIC expression reduced the levels of xCT (SLC7A11) and glutamate release in glioma cells." (PMID 36647117, 2023). "The IDH1- mutated glioma had significantly increased SLC7a11 expression following CMD, while the IDH1-wild-type glioma trended towards an increase of SLC7a11 (p = 0.08) (d ii.)." (PMID 36864031, 2023). "Using the expression profile data from TCGA and GTEx, we analyzed the mRNA levels of SLC7A11 in patients with glioma." (PMID 38162649, 2023). "Previous studies have shown that the cystine/glutamate antiporter xCT (SLC7A11) is responsible for the glutamate release pathway in gliomas." (PMID 36647117, 2023). "Recent studies have shown that inhibition of amino acid transporters, such as system x_c^– and SLC7A11, can induce ferroptosis in glioma cells and suppress tumor growth in glioma models." (PMID 38020609, 2023). "Taken together, these results demonstrate that CIC regulates glutamate release in glioma cells possibly via SLC7A11." (PMID 36647117, 2023). "C-myc induces expression of the SLC7A11 gene, which is upregulated in several cancer types and is a known driver of tumor cell malignancy in glioma." (PMID 36834608, 2023). "In glioma, hypoxia augments tumor resistance to Sulfasalazine-induced ferroptosis by increasing SLC7A11 expression through activation of the PI3K/AKT/HIF-1α pathway." (PMID 37978473, 2023). "In short, we identified SLC7A11 as a vital regulator gene for the ferroptosis defense ability of glioma cells under hypoxic conditions." (PMID 36439690, 2022). "Activating transcription factor 4 (ATF4) can increase neovascularization within gliomas and shape neovascularization in a SLC7A11-dependent manner." (PMID 36185243, 2022). "We then analyzed the public data and found that the expression of SLC7A11 was positively correlated with HIF-1α in 257 glioma tumor samples." (PMID 36439690, 2022). "High expression of OTUB1 was also found in clinical samples of glioma and was positively correlated with SLC7A11 expression." (PMID 36185243, 2022). "In conclusion, hypoxia enhanced glioma resistance to SAS-induced ferroptosis by upregulating SLC7A11 via activating the PI3K/AKT/HIF-1α axis." (PMID 36439690, 2022). "ATF4 has also been found to mediate the therapeutic resistance of temozolomide to glioma by upregulating SLC7A11 to absorb more cystine, promote the synthesis of glutathione, and neutralize reactive oxygen species." (PMID 35864117, 2022). "SLC7A11 was reported to be expressed at higher levels in GBM patient biopsies or glioma cell lines than in normal brain tissue." (PMID 36091118, 2022). "Here, we found that hypoxia significantly suppressed SAS-induced ferroptosis by upregulating SLC7A11 expression in the U87 and U251 glioma cell lines." (PMID 36439690, 2022). "After knockdown of circCDK14 in glioma cells, protein levels of SLC7A11 and GPX4 decreased significantly and Fp became more sensitivity." (PMID 35002529, 2022).